IL11RA (interleukin 11 receptor subunit alpha)
Description:
Receptor for interleukin-11 (IL11). The receptor systems for IL6, LIF, OSM, CNTF, IL11 and CT1 can utilize IL6ST for initiating signal transmission. The IL11/IL11RA/IL6ST complex may be involved in the control of proliferation and/or differentiation of skeletogenic progenitor or other mesenchymal cells (Probable). Essential for the normal development of craniofacial bones and teeth. Restricts suture fusion and tooth number. [Soluble interleukin-11 receptor subunit alpha]: Soluble form of IL11 receptor (sIL11RA) that acts as an agonist of IL11 activity. The IL11:sIL11RA complex binds to IL6ST/gp130 on cell surfaces and induces signaling also on cells that do not express membrane-bound IL11RA in a process called IL11 trans-signaling. [Isoform HCR2]: Soluble form of IL11 receptor (sIL11RA) that acts as an agonist of IL11 activity. The IL11:sIL11RA complex binds to IL6ST/gp130 on cell surfaces and induces signaling also on cells that do not express membrane-bound IL11RA in a process called IL11 trans-signaling.
Synonyms: CRSDA
Tractability: Antibody: UniProt places it where antibodies can reach, with high confidence; its Gene Ontology location is reachable by antibodies, with high confidence; UniProt predicts a signal peptide or a membrane-spanning region; the Human Protein Atlas places it where antibodies can reach. Other modalities: an approved drug acts on it.
Target class: Membrane receptor
Gene: Protein-coding gene on chromosome 9 (34,651,582 to 34,661,902, forward strand). Ensembl gene ENSG00000137070.
Subcellular location: Membrane (Interleukin-11 receptor subunit alpha); Secreted (Soluble interleukin-11 receptor subunit alpha); Secreted (Isoform HCR2)
Subcellular location (Human Protein Atlas): Plasma membrane; Vesicles; Predicted to be secreted
Pathways (Reactome):
Immune System: IL-6-type cytokine receptor ligand interactions
Gene Ontology:
Molecular function: interleukin-11 receptor activity; protein binding; interleukin-11 binding; transmembrane signaling receptor activity; cytokine receptor activity
Biological process: developmental process; head development; interleukin-11-mediated signaling pathway; cytokine-mediated signaling pathway; positive regulation of cell population proliferation; embryo implantation
Cellular component: extracellular region; membrane; external side of plasma membrane; plasma membrane; receptor complex
Genetic constraint (gnomAD): Loss-of-function variants: 49 observed, 57.67 expected, observed/expected ratio (o/e) 0.85, 90% interval 0.68 to 1.08. The upper end of that interval is the gene's LOEUF score, 1.08, which puts it in group 4 of 6, group 1 being the genes least tolerant of losing a copy. Missense variants: 492 observed, 559.45 expected, observed/expected ratio (o/e) 0.88, 90% interval 0.82 to 0.95. Synonymous variants: 195 observed, 228.52 expected, observed/expected ratio (o/e) 0.85, 90% interval 0.76 to 0.96.
Gene-disease validity (ClinGen):
ClinGen rates the evidence that IL11RA causes each of these diseases.
craniosynostosis and dental anomalies (autosomal recessive): Definitive.
Homologues: Orthologues: chimpanzee IL11RA (98% identical), macaque GALT (91% identical), pig IL11RA (90% identical), dog IL11RA (89% identical), mouse Il11ra1 (84% identical), mouse Il11ra2 (83% identical), mouse Il11ra3 (83% identical), rat Il11ra1 (82% identical), guinea pig IL11RA (81% identical), rabbit IL11RA (77% identical), tropical clawed frog il11ra (40% identical), zebrafish il11ra (13% identical), and 3 more. Paralogues in human: CNTFR (22% identical), CSF3R (20% identical), IL6R (18% identical), IL12RB2 (16% identical), LIFR (16% identical), EBI3 (15% identical), IL6ST (14% identical), PRLR (13% identical), IL27RA (13% identical), CRLF1 (13% identical), IL23R (13% identical), OSMR (13% identical), and 11 more.
Diseases named in the same sentence as IL11RA in open-access papers:
IL11RA is named in the same sentence as 63 diseases in open-access papers, as found by Europe PMC text mining. Sharing a sentence is not in itself a finding about the gene and the disease. The quoted sentences say what the papers report.
craniosynostosis (16 papers, 2013 to 2025). Craniosynostosis is defined as the premature fusion of one or more cranial sutures leading to secondary distortion of skull shape resulting in skull deformities with a variable presentation. "The skeletal phenotype is probably influenced by impaired IL-11 signaling, given that individuals with IL11RA mutations manifest with craniosynostosis and dental malformations." (PMID 40040707, 2025). "Beginning in 2011, several reports have been published linking pathogenic variants within the IL11RA gene to craniosynostosis ([MIM: 614188]11–17, for an overview see18)." (PMID 37596289, 2023). "Craniosynostosis is seen in up to 40% of Il11ra1 knockout mice, which has also been reported in humans with homozygous IL11RA loss-of-function mutations." (PMID 37629170, 2023). "Missense mutations in interleukin-11 receptor alpha subunit (IL11RA) have been implicated in Crouzon-like craniosynostosis, which is characterized by multiple suture fusions and dental anomalies, such as delayed tooth eruption or supernumerary teeth." (PMID 35451466, 2022). "Only those with biallelic IL-11Rα mutations sometimes manifest abnormalities, such as mild craniosynostosis, scoliosis, joint laxity, and delayed tooth eruption, but are still otherwise healthy." (PMID 35273577, 2022). "Several human studies have identified individuals with IL11RA mutations who have mild features of craniosynostosis, joint laxity, scoliosis and delayed tooth eruption, although ascertainment bias has been suggested." (PMID 34239012, 2021). "IL11RA encodes the IL-11 receptor, and mutations in this gene cause autosomal recessive Crouzon‐like craniosynostosis and affect thymus immune function." (PMID 33095808, 2020). "Here, we demonstrate that mutations in the IL11RA gene cause autosomal recessive Crouzon-like craniosynostosis or syndromic pansynostosis with mild craniofacial phenotype via impaired interleukin-11 mediated signaling, based on mutations in five families." (PMID 24498618, 2013). "This study demonstrates that mutations in the IL11RA gene cause an autosomal recessive Crouzon-like craniosynostosis." (PMID 24498618, 2013). "An extended IL11RA mutation screen was performed in a cohort of 79 patients with an initial clinical diagnosis of Crouzon syndrome, pansynostosis, or unclassified syndromic craniosynostosis." (PMID 24498618, 2013). "Of these 17 patients, 9 had syndromic craniosynostosis (Crouzon, n = 7; Saethre-Chotzen, n = 1; IL11RA, n = 1), 1 had multisuture synostosis, and 7 had isolated craniosynostosis (sagittal, n = 6; unicoronal, n = 1)." (PMID 37927034, 2024). "Loss of function (LOF) in IL11RA infers IL11 signaling as important for fertility, fibrosis, inflammation and incompletely penetrant craniosynostosis." (PMID 34239012, 2021). "Individuals with IL-11RA deficiency present with craniosynostosis and dental anomalies, but do not exhibit significant immunodeficiency." (PMID 40040707, 2025). "The IL11RA gene is, however, involved in “craniosynostosis with dental anomalies” (OMIM #614188)." (PMID 35191116, 2022). "Except mild craniosynostosis, delayed tooth eruption and variable joint laxity, humans with null mutations in IL-11RA have no other major abnormalities." (PMID 34054526, 2021). "Interestingly, until now, only craniosynostosis patients with variants within the IL11RA gene have been described, but no patients with variants in IL11, which encodes the cytokine itself, are known." (PMID 37596289, 2023). "Thus, the frontal bossing, and perhaps the clubfeet, were early indicators of craniosynostosis, while the neurological features may or may not be explained by the IL11RA variants." (PMID 35191116, 2022). "In contrast to individuals with partial LOF IL6ST mutations, complete IL11RA deficiency, or STAT3-DN mutations, individuals with IL6ST-DN do not exhibit craniosynostosis, most likely because of remaining functionality in IL-11 signaling." (PMID 40040707, 2025).
craniosynostosis (continued). "We did not observe specific phenotypic differences between IL11RA and FGFR2 caused craniosynostosis." (PMID 24498618, 2013). "All 13 coding exons of the IL11RA gene were screened by DNA sequencing in a cohort of 79 patients with a diagnosis of either CS, pansynostosis, or nonclassified syndromic craniosynostosis." (PMID 24498618, 2013).
osteosarcoma (11 papers, 2010 to 2025). A usually aggressive malignant bone-forming mesenchymal neoplasm, predominantly affecting adolescents and young adults. "Another study also demonstrated that BMTP‐11, a drug targeting IL‐11RA, reduced osteosarcoma tumour growth and lung metastasis formation, although this drug was associated with renal toxicity." (PMID 40673604, 2025). "In line with this, one report on osteosarcoma lung metastases showed that CAR‐T cells against IL‐11RA decreased tumour growth in xenograft models." (PMID 40673604, 2025). "In fact, in a study conducted by Lewis and co-workers, targeting IL-11Rα using the proapoptotic agent BMTP-11 significantly decreased the overall tumourigenesis of osteosarcoma tumours." (PMID 38248304, 2024). "As regards other bone-related cancers and their progression to metastasis, IL-11Rα is a cell surface marker of tumour progression and correlates with poor prognosis in patients with osteosarcoma." (PMID 34201209, 2021). "Anti-IL-11Rα CAR T cells were effective against primary osteosarcoma and were able to reduce metastatic dissemination with 3 of 5 mice free of pulmonary metastases." (PMID 33207697, 2020). "Other CAR T cell targets, such as IL-11Rα and B7-H3 have also been tested in various sarcoma subtypes, including osteosarcoma and Ewing sarcoma." (PMID 33207697, 2020). "SCAN-ACT identified 174 monospecific CAR-T targets in GBM, including several established GBM CAR-T targets such as CD276, EGFR, IL13RA2, ROBO1, as well as targets studied in different diseases like GPC2 in neuroblastoma, IL11RA in osteosarcoma, or DLL3 in lung cancer." (PMID 40814001, 2025). "In addition, IL-11Rα has been identified as a prognostic marker correlating negatively with patient survival and a potential candidate for drug intervention in osteosarcoma." (PMID 38248304, 2024). "The same authors show that IL-11Rα and its ligand, IL-11, are specifically upregulated in human metastatic osteosarcoma cell lines and that the engagement of this autocrine loop leads to tumour cell proliferation, invasion, and anchorage-independent growth in vitro." (PMID 34201209, 2021). "The data suggest that anti-IL-11Rα CAR T therapy may be a promising option for osteosarcoma patients with pulmonary metastases." (PMID 33207697, 2020). "Moreover, IL-11Rα-CAR+ T cells successfully killed human osteosarcoma cells and induced the regression of osteosarcoma with lung metastases." (PMID 27683579, 2016). "Conceivably, combining IL-11Rα-CAR+ T cells with other therapies may produce a clinically beneficial response in patients with osteosarcoma." (PMID 27683579, 2016). "IL11Rα protein is a proposed candidate target for both human osteosarcoma and also bone metastasis." (PMID 20553623, 2010). "Currently, potential effective targets for CAR-T cell therapy in osteosarcoma include HER2, IGF1R, ROR1, EphA2, CSPG4, folate receptor with EC17, B7-H3, GD2, NKG2D, ALCAM/CD166, IL-11Rα, and FAP." (PMID 38187386, 2023). "Interleukin 11 receptor subunit alpha (IL11RA), a stromal cell-derived cytokine, is overexpressed in patients with human osteosarcoma and advanced breast cancer with bone metastasis." (PMID 29507648, 2018). "A similar design has successfullybeen tested for the pair IL11Rα/nonapeptide IL11 (IL11Rα is typicallyoverexpressed on osteosarcoma, gastric, intestinal, breast, and prostate cancercells)." (PMID 28461969, 2017). "Additional evidence has demonstrated that IL-11Rα was overexpressed in primary and metastatic osteosarcoma, but not expressed in the adjacent normal lung tissue, or in major organs, such as brain, heart, and kidney." (PMID 27683579, 2016).
infertile (8 papers, 2004 to 2024). "Female mice with a null mutation in the gene encoding interleukin-11 receptor α (IL-11Rα) are infertile due to disrupted decidualization, suggesting a critical role for IL-11 and its target genes in the decidual response." (PMID 15537430, 2004). "Female interleukin-11 receptor α (IL-11Rα) deficient mice are infertile due to disrupted decidualization, suggesting a critical role for IL-11 and its target genes in implantation." (PMID 15537430, 2004). "Interestingly, to our knowledge, only one further mouse model, i.e. mice deficient for interleukin 11 receptor alpha (IL-11Rα), exists, which displays this unique form of infertility." (PMID 30301918, 2018). "It has also been shown that BIRC5 gene expression is significantly repressed in the deciduae of interleukin-11 receptor alpha null (IL-11Rα) mice, which are infertile due to defective decasualization and impaired trophoblast invasion." (PMID 39687493, 2024). "In contrast to the present study IL-11, IL-11Rα and LIF staining were decreased in glandular epithelial cells in women with endometriosis associated infertility." (PMID 18047677, 2007). "Endometrial protein abundance for IL-11, pSTAT3, IL-11Rα and LIF was compared in women with primary unexplained infertility and normal fertile women." (PMID 18047677, 2007). "We hypothesized that IL-11, IL-11Rα, LIF and pSTAT3 are dysregulated in endometrium from women with unexplained infertility during the 'window of implantation'." (PMID 18047677, 2007). "While all tissues from control and infertile women stained for IL-11Rα, the intensity ranged from minimal to high and was not different between infertile and fertile women." (PMID 18047677, 2007). "Mice lacking IL-11Rα are infertile due to defective uterine response to implantation." (PMID 22433466, 2012). "IL-11, pSTAT3, IL-11Rα and LIF staining was overall low and patchy or absent in luminal epithelium of both infertile and fertile women." (PMID 18047677, 2007).
breast carcinoma (7 papers, 2010 to 2025). "IL11 was found to be positively associated with immune cell infiltration in HCC, while IL11RA was associated with a better prognosis in breast cancer." (PMID 35145511, 2021). "A role for IL-11 signaling in breast cancer has been less well-described, but elevated levels of IL-11 and IL-11Rα are associated with poor patient outcomes and both IL-11 and IL-6 are associated with breast cancer metastasis into bone." (PMID 32765502, 2020). "IL11 and IL11Rα transcript levels are linked to breast cancer prognosis - breast tumours with a poor prognostic index show a high level of IL11." (PMID 20553623, 2010). "In breast cancer cell lines, IL11RA overexpression induces reduction of cell proliferation, which supports good prognosis." (PMID 38398114, 2024). "Previous studies of IL11RA suggest that it has a tumorigenic effect in gastric, endometrial, colorectal, and breast cancer by suppressing inflammation and promoting proliferation." (PMID 38398114, 2024). "IL-11/IL-11Rα is connected to bone metastasis and could potentially predict bone metastases from breast cancer." (PMID 40584290, 2025). "Furthermore, in patients with advanced breast cancer, there was a reported positive connection between the expression of IL-11Rα in tumor cells and the incidence of bone metastases." (PMID 40584290, 2025). "Overexpression of genes such as IL11RA, BST2 and GAS6 were important for pathogenesis of many cancer types such as gastric cancer, breast cancer, and ovarian cancer, but high expression of these genes may be responsible for advancement of GBM." (PMID 31137733, 2019).
prostate carcinoma (7 papers, 2007 to 2024). A carcinoma that arises from epithelial cells of the prostate gland. "Whether IL-11RA is causative in prostate cancer growth needs to be investigated in further studies." (PMID 17712417, 2007). "This synergistic relationship not only reinforces the contributory role of IL-11/IL-11RA signalling in chemoresistance but also showcases the potential of targeted therapies to improve clinical outcomes in prostate cancer." (PMID 38429845, 2024). "Previous research has demonstrated the IL11/IL11RA axis was activated under hypoxia and promoted the proliferation of prostate cancer cells." (PMID 33197880, 2020). "In the recent first in human study, six human prostate cancer patients were treated with a site-targeted peptidomimetic drug that targets IL11Rα, which increased apoptosis in bone metastatic lesions." (PMID 28186993, 2017). "Increased expression of IL-11Rα occurs in prostate cancer and has been suggested as a candidate target for metastatic prostate cancer lesions." (PMID 27683579, 2016). "Through direct selection of peptide libraries in patients, we isolated a ligand peptide mimicking IL-11 from the prostate vasculature and proposed the IL-11Rα as a target during the progression of prostate cancer." (PMID 18941632, 2008). "Our findings are supported by a number of studies in other epithelial-derived tumour types, where impaired IL11Rα signalling reduced gastric and prostate cancer growth and metastasis, further strengthening the rationale for therapeutically targeting IL11Rα in endometrial cancer." (PMID 28186993, 2017). "Additionally, overexpression of IL-11Rα occurs in both metastatic breast cancer and prostate cancer, implying the involvement of IL-11Rα in bone metastases." (PMID 27683579, 2016). "Because of the increased stage-specific expression of IL-11Rα on prostate cancer cells and tumor endothelium during disease progression, this peptide could serve as a ligand for the targeted delivery of drugs and imaging agents in patients with prostate cancer." (PMID 21258295, 2011). "This BAC clone contained two genes, IL-11RA and DCTN3, which were already thought to play a role in prostate cancer growth." (PMID 17712417, 2007). "We, therefore, screened 20 primary prostate cancer samples and found 75% of the tumors harboring an IL-11RA copy number gain alone, none of DCTN3 alone, and 10% of both genes." (PMID 17712417, 2007). "IL-11RA showed a significant increase in gene copy number above normal in CWR22 and CWR22-Rv1 and in 15 out of 20 (75%) primary prostate cancer tumor samples." (PMID 17712417, 2007).
gastric cancer (6 papers, 2015 to 2024). A primary or metastatic malignant neoplasm involving the stomach. "We used this dataset to evaluate the expression patterns of YAP1, STAT3, IL11, IL6, TEAD1, IL6ST, and IL11RA in gastric cancer patients within the four TME subtypes." (PMID 37957015, 2024). "Puma and Bad were not altered by treatment with an IL11 Ra mutein antagonist in a mouse model of gastric cancer, however we demonstrated their induction in response to IL11Rα Ab combination treatment with doxorubicin chemotherapy." (PMID 28186993, 2017). "Aberrant expression of IL-11 and its receptor IL-11Rα was found in gastric cancer tissues, and correlated with Lauren’s classification, tumor invasion and vessel infiltration." (PMID 25929737, 2015).
colorectal cancer (4 papers, 2018 to 2024). A primary or metastatic malignant neoplasm that affects the colon or rectum. "Many studies had shown that IL11Rα was highly expressed in colorectal cancer cells and was often used as a target for immunotherapy." (PMID 38067271, 2023). "The methylation of five genes (AHCYL2, IL11RA, SEMA6D, BIRC3, and HADHB) was associated with tumors, and four genes (IL11RA, CHL1, SEMA6D, and BIRC3) were associated with colorectal cancer." (PMID 29507648, 2018).